IFNAR1 (interferon alpha and beta receptor subunit 1)
Diseases named in the same sentence as IFNAR1 in open-access papers (continued):
Sharing a sentence is not in itself a finding about the gene and the disease.
cancer (continued). "Mutation of the IFNAR1 gene by CRISPR/Cas9 editing removed detectable IFNAR1 expression on the cell surface and rendered cancer cells insensitive to exogenous IFNβ stimulation." (PMID 32355214, 2020). "The exciting discovery that association with SHMT2 is controlled by PLP promises pharmaceutical compounds able to modify the abundance of IFNAR1, allowing new therapies for cancer and autoimmune disorders." (PMID 33142801, 2020). "Pronounced immune responses were provoked after ionizing radiation of tumors from 4 mouse cancer cell lines with Ifnar1 knockout." (PMID 31483286, 2019). "Most importantly, reintroduction of Serpinb9 expression in Ifnar1-KO cancer cells abrogated their enhanced response to IR." (PMID 31483286, 2019). "Our panel of Ifnar1-KO cancer cells expressed PD-L1 at approximately the same extent as their WT counterparts, albeit with considerable variation among cell lines." (PMID 31483286, 2019). "Noteworthy were a number of hub genes like TLR4, FAS, HLA-DQB1, HLA-DQA1, F2, HLA-C, IFNAR1, which link complex diseases related to metabolic, immunological, infectious, cardiovascular, neuro-psychiatric disorders and cancer." (PMID 18782426, 2008). "Importantly, antibody-mediated binding to the cancer cell surface locally increases the concentration of IFNα R149A such that this compensates for its reduced capacity to bind and activate IFNAR1/2." (PMID 40243928, 2025). "Other non-significant cancer-associated genes with significant isoform switch expression include IFNAR1, SMAD3, and LAMA3." (PMID 38059347, 2024). "VPS9D1-AS1 mediates crosstalk between T cells and cancer cells by regulating IFNAR1." (PMID 36458816, 2022). "We abolished type I IFN signaling in cancer cells by genetic elimination of its receptor, IFNAR1." (PMID 31483286, 2019). "Serpinb9 was critical in enhancing the vulnerability of Ifnar1-KO cancer cells in our study, consistent with its known role as an inhibitor of granzyme B, an important mediator of T and NK cytoxicity, including killing of cancer cells." (PMID 31483286, 2019). "We identified Serpinb9 as a critical component depleted in the Ifnar1-KO cancer cells." (PMID 31483286, 2019). "We now asked whether mice in which Ifnar1-KO MC38 tumors had regressed retained systemic antitumor immunity to challenge with either WT or Ifnar1-KO cancer cells." (PMID 31483286, 2019). "However, analysis of the Cancer Genome Atlas (TCGA) database revealed high expression of Ifnar1 and Ifnar2 in a range of cancer entities and human cancer cell lines showed expression of Ifnar1 and Ifnar2." (PMID 28248314, 2017). "Besides, the impact on IFN and downregulation of IFNAR1 has also been studied in cancer models." (PMID 33746965, 2021). "Thus, Ifnar1-KO cancer cells were more vulnerable to CD8+ T cell–mediated killing in culture." (PMID 31483286, 2019). "Moreover, all the murine cancer cells tested in our in vivo studies expressed Ifnar1." (PMID 28248314, 2017). "HCV-1b core protein also induces miR-93-5p upregulation and inhibits the IFN signaling pathway by directly targeting IFNAR1, whereas the miR-93-5p-IFNAR1 axis regulates STAT1 phosphorylation, which plays a crucial role in cancer development." (PMID 39228892, 2024). "By 6 days after radiation, the Ifnar1-KO MC38 tumors had increased infiltration of CD8+ T cells and a much smaller percentage of cancer cells, consistent with the decreasing volumes of Ifnar1-KO tumors at that time." (PMID 31483286, 2019). "Emodin enhances the antiproliferative effect of IFN-α on cancer cells by promoting the activation of JAK/STAT signaling, which is achieved via inhibition of 26S proteasome-stimulated IFNAR1 degradation." (PMID 26683360, 2016). "It transpires that Serpinb9 (serine protease inhibitor) is an essential factor absent in IFNAR1 knock out cancer cells." (PMID 38672681, 2024).
cancer (continued). "Following treatment with vehicle or DMXAA (20 mg/kg, i.p. at d3 and d7), we found that DMXAA treatment effectively attenuated cancer-induced mechanical allodynia and cold allodynia in WT mice but not Ifnar1−/− mice." (PMID 34315904, 2021). "The resulting heatmap showed that in the majority of malignancies, TILs were significantly correlated with multiple representative ICD mediators, such as CALR, LRP1, ANXA1, FPR1, TLR3, IFNAR1, PANX1, and P2RX7." (PMID 33299118, 2020). "This response to cancer cells lacking Ifnar1 depended upon CD8+ T cell–based immunity and was mediated by enhanced susceptibility to CD8+ T cell–mediated killing." (PMID 31483286, 2019). "In conclusion, we found that apigenin, distributed widely in fruits and vegetables, potentiates the inhibitory effects of type I IFNs on cancer cell viability by the activation of JAK/STAT pathway through the inhibition of 26S proteasome and stabilization of IFNAR1." (PMID 27356910, 2016). "We further detected the CD4+ IFNAR1 levels and CD8+ PD1 levels of peripheral blood lymphocytes in 15 patients with VPS9D1-AS1 positive expression and 16 patients with VPS9D1-AS1 negative expression in cancer tissues." (PMID 36458816, 2022).
bacterial infection (16 papers, 2014 to 2025). "Moreover, GSEA identified IFNAR1, ISG15 and IL10 as potential regulators of both bacterial infection and immune response." (PMID 37876725, 2023). "Interestingly, there was a 2-fold increase in neutrophils in the BALF of Ifnar1−/− mice after bacterial infection, compared to WT mice, independent of whether mice had preceding IAV infection." (PMID 27143388, 2016). "The necrotic liver injury was not due to bacterial infection, as culture of liver homogenates from WNV-infected anti-IFNAR1-treated SPF mice did not yield bacterial growth." (PMID 37749080, 2023).
neurological disease (15 papers, 2016 to 2025). "In addition, ZIKV infection of adult Ifnar1-KO mice was found to reach the spinal cord and cause features of neurological disease, including hindlimb weakness and paralysis, before the infected mice succumbed to the infection." (PMID 29976926, 2018). "N153SLSL/LSLPcp2-cre;Ifnar1−/− mice develop similar neurological disease as N153SLSL/LSLPcp2-cre mice, as measured by the beam walking test." (PMID 41166304, 2025). "INKV-inoculated Ifnar1-/- mice died at 2 dpi, while JCV-inoculated Ifnar1-/- mice all developed neurological disease or died at 3–4 dpi." (PMID 35245345, 2022). "We noted a significant difference in weight loss and a marked difference in the signs of neurological disease between the CD4 depleted and control indicating that CD4+T cells are important for protection of the Ifnar1-/- mice from a CNS associated disease." (PMID 30212537, 2018). "However, we found that Ifnar1-/-, Irf3-/-xIrf7-/- DKO, and Mavs-/-xUnc93b1.3D DKO mice inoculated with INKV all developed neurological disease." (PMID 35245345, 2022). "The lack of sufficient IFN signaling in the Ifnar1-/-, Irf3-/-xIrf7-/- and Mavs-/-xUnc93b1.3D mice, which all developed neurological disease, may allow JCV to replicate so abundantly that it can overcome this deficiency and induce BBB breakdown." (PMID 35245345, 2022). "However, we cannot exclude the possibility that Ifnar1–/– mice infected with SVNI succumb to systemic disease, rather than a disease of the CNS, and therefore, amelioration of neurological disease by CBE may not be sufficient to alleviate disease symptoms in the case of the Ifnar1–/– mouse." (PMID 32831144, 2020).
neurodegenerative disease (6 papers, 2016 to 2024). A disorder of the central nervous system characterized by gradual and progressive loss of neural tissue and neurologic function. "Supporting a possible role for IFN-I in such disease exacerbation we and others have shown that brain IFNAR1 contributes to progression and severity of neurodegenerative disease." (PMID 33442686, 2021). "We examined previously characterized measures of disease progression to assess the impact of IFNAR1−/− on progression of this fatal neurodegenerative disease." (PMID 30680794, 2019). "Targeting Ifnar1/IFN‐β signaling may therefore highlight new therapeutic strategies for AMD and potentially other chronic inflammatory and degenerative diseases of the retina." (PMID 27137488, 2016). "Anifrolumab, an IFNAR1 monoclonal antibody that recently received FDA approval to treat SLE, is another potential drug to be used against the cytosolic DNA sensing pathway in neurodegenerative diseases since symptoms of SLE include significant neurological dysfunction." (PMID 38467840, 2024).
inflammation (5 papers, 2014 to 2024). Aberrant reaction of the microcirculation characterized by movement of fluid and leukocytes from the blood into extravascular tissues. "Pancreatic inflammation in mice deficient in IFNAR1 ubiquitination was paralleled with an altered balance between pro-inflammatory and anti-inflammatory cytokines (e.g. TNFα and IL10) and increased expression of CCL2." (PMID 24480543, 2014). "WT and Ifnar1−/− mice were intranasally treated with AP + OVA for a long period to develop chronic eosinophilic sinonasal inflammation." (PMID 30455684, 2018).
infectious disease (4 papers, 2018 to 2025). A disorder directly resulting from the presence and activity of a microbial, viral, or parasitic agent in humans. "DS population has high risk for infectious diseases due to genetic susceptibility in some genes related to immunity such as IFNAR1/2 and HSA21 genes and the gene controlling TMPRSS2 receptor." (PMID 37521827, 2022). "Discovery of additional genetic associations of IFNAR1 signaling components and susceptibility of TB and other infectious diseases in future studies will assist in validating the observations reported here and in dissecting the complex function of IFNs in humans." (PMID 29311663, 2018).
kidney disease (3 papers, 2016 to 2023). "Previous studies have shown IFNβ and IFNAR1/2 blockade improved kidney function and histology in kidney disease models suggesting the importance of IFN signaling in kidney disease." (PMID 36732547, 2023).
hematopoietic diseases (1 paper, 2024). "Therefore, the beneficial effect of Ifnar1 deletion in Abin1Q478H/Q478H mice serves as a promising novel strategy for treating hematopoietic deficiencies and may offer new opportunities for therapeutic interventions in patients suffering from hematopoietic diseases, including del(5q) MDS." (PMID 38009796, 2024).
intestinal disease (1 paper, 2023). "To investigate the role of type I and type III IFNs in controlling MNV intestinal disease, we also infected Ifnar1−/− and Ifnlr1−/− mice with each virus." (PMID 37142696, 2023).
peripheral neuropathies (1 paper, 2023). "In this study, we observed an increase in C5a levels in the brains of ZIKV-infected Ifnar1−/− mice, thereby suggesting its contribution to peripheral neuropathies." (PMID 37191498, 2023).
IFNAR1 also shares sentences with these, for which no sentence is quoted: viral disease (8 papers); microcephaly (4); psoriasis (4); rubella (4); AIDS (3); arbovirus infection (3); glioblastoma (3); lymphopenia (3); viral hepatitis (3); Anxiety (2); Ataxia (2); breast (2); cervical cancer (2); combined immunodeficiency (2); cutaneous leishmaniasis (2); dengue virus infection (2); head and neck cancer (2); lupus nephritis (2); mesothelioma (2); mumps (2); myocardial infarction (2); neutropenia (2); peritonitis (2); rheumatic disease (2); rheumatoid arthritis (2); vasculopathy (2); achromatopsia (1); acute respiratory distress syndrome (1); adenocarcinoma (1); Airway obstruction (1).
A further 105 diseases each share a sentence with IFNAR1 in 1 paper.